ENSG00000252719
Gene: Small nucleolar RNA gene on chromosome X (139,909,904 to 139,910,034, forward strand). Ensembl gene ENSG00000252719.
Homologues: Paralogues in human: SNORA18 (78% identical).